CASP1 (caspase 1)
Diseases named in the same sentence as CASP1 in open-access papers (continued):
Sharing a sentence is not in itself a finding about the gene and the disease.
dermatitis (18 papers, 2016 to 2025). An inflammatory process affecting the skin. "Regarding the involvement of other caspases deregulation in skin disease, caspase-1 is upregulated in androgenic alopecia, while caspase-8 deficiency in keratinocytes triggers chronic skin inflammation in mice." (PMID 39625520, 2024). "In the present study, we assess the risk of mortality in septic conditions, its pathogenesis, and its underlying causes using a mouse dermatitis model: KCASP1Tg mice, which overexpress keratin 14-driven caspase-1." (PMID 38203647, 2023). "In a chronic proliferative dermatitis animal model, Nlrp3- or Casp1- and -11-deficient mice showed reduced skin inflammation and delayed disease onset, suggesting that the inflammasome might be an important trigger for disease development." (PMID 32528469, 2020). "A study using a long-lasting dermatitis mouse model that overexpressed human caspase-1 in keratinocytes (Kcasp1Tg) investigated the effects of deleting IL-17A and IL-17F on visceral complications." (PMID 39519167, 2024). "To evaluate the psychological symptoms of uncontrolled dermatitis, we conducted an experimental behavioral analysis using a mouse model of spontaneous dermatitis, keratin 14-driven caspase-1 overexpressing (KCASP1Tg) mice." (PMID 36983014, 2023). "We employed spontaneous dermatitis model mice overexpressing human caspase-1 in the epidermal keratinocyte (Kcasp1Tg)." (PMID 36982506, 2023). "We employed spontaneous skin inflammation mice models overexpressing human caspase-1 in the epidermal keratinocytes." (PMID 35008464, 2021). "We addressed this problem by using keratin 14-specific human caspase-1 overexpressing transgenic (KCASP1Tg) mice, which are accepted as a spontaneous dermatitis model." (PMID 32397568, 2020). "We employed model mice of spontaneous skin inflammation, specifically overexpressing human caspase-1 in the epidermis." (PMID 32443893, 2020). "We addressed this problem using keratin 14-specific caspase-1 overexpressing transgenic (KCASP1Tg) mice with severe erosive dermatitis from 8 weeks of age, followed by re-epithelization." (PMID 32397568, 2020). "IL18 is essential for the induction of dermatitis by the epidermis-restricted expression of caspase 1, the enzyme that generates active IL18 from its precursor." (PMID 27431613, 2016). "Sharpincpdm mice crossed with mice lacking interleukin-1β converting enzyme (Ice−/− mice), which are deficient in both caspase-1 and caspase-11, showed a delayed onset and alleviation of skin inflammation." (PMID 40006996, 2025). "IL-17 and IL-22 enhance skin inflammation via the ROS-NLRP3-caspase-1 pathway." (PMID 32528469, 2020). "Therefore, we evaluated the influence of skin inflammation on sperm dysfunction in an acute spontaneous dermatitis mice model, keratin 14-specific human caspase-1-overexpressing transgenic (KCASP1Tg) mice." (PMID 32825298, 2020). "It is possible that other inflammasome-dependent cytokines and effector molecules downstream of caspase-1 could be involved in cellular dysregulation and/or dermatitis development." (PMID 27892465, 2016). "Enhanced cleavage products of caspase-1, GSDMD, and IL-1β were observed in both imiquimod-induced psoriasis-like dermatitis (IIPLD) mouse epidermis and M5 (simulating psoriatic inflammatory challenge)-treated keratinocytes in vitro." (PMID 40332377, 2025). "In brief, peptide caspase-1 inhibitors such as z-WEHD-FMK and Ac-YVAD are used for the treatment of dermatitis." (PMID 39625520, 2024). "In IMQ-treated Nlrp3−/− mice, psoriasiform lesions were comparable to those of normal controls; however, caspase-1 activity in the skin was markedly decreased, indicating that the NLRP3 inflammasome was required for caspase-1 activation, but dispensable for skin inflammation." (PMID 32528469, 2020).
dermatitis (continued). "Transgenic mice over-expressing the human caspase-1 precursor gene in epidermal keratinocytes (CASP1 transgenic mice) showed elevated serum levels of IgE and IgG1 at the age of 8 weeks, and mild pruritic dermatitis around the eyes and ears at the age of 16 weeks." (PMID 28434120, 2017).
endotoxemia (18 papers, 2009 to 2022). "The mechanism of protection against cisplatin-induced AKI and endotoxemia-induced AKI in caspase-1 deficient mice remains to be determined." (PMID 20182538, 2009). "Treatment of 1,2-diol significantly inhibited the cleavage of GSDMD and Caspase-1 in lung tissue in endotoxemia mice." (PMID 35222388, 2022). "Neutralizing extracellular HMGB1 with monoclonal antibodies confers considerate protection against Caspase-1/Caspase-11-mediated lethality during endotoxemia." (PMID 30134814, 2018). "We further demonstrated that caspase-1 and caspase-11 differentially contributed to the host defense against A. fumigatus infection and to endotoxemia." (PMID 28345580, 2017). "Moreover, we discovered the rising gene and protein expression of an inflammasome complex containing NLRP3, ASC, and cleaved caspase 1 in endotoxemia colons compared to the control ones, which was also decreased by BRD4 inhibition." (PMID 33679744, 2021). "Further, both caspase-1 and caspase-11 contributed to the host defense against infection with A. fumigatus, whereas caspase-11 predominantly contributed to lethality during LPS-induced endotoxemia." (PMID 28345580, 2017). "Importantly, we found increased caspase-1 activity, the effector protein of the inflammasome, in the livers of aged rats during endotoxemia compared with young rats." (PMID 25847140, 2015). "In conclusion, our findings indicate that glibenclamide could ameliorate myocardial injury and reducing IL-1β and TNF-α possibly through inhibiting Nalp3 inflammasomes and Caspase-1 signaling under LPS-induced endotoxemia in STZ diabetic mice." (PMID 25077824, 2014). "Caspase-1 deficient mice are protected against cisplatin-induced AKI and endotoxemia-induced AKI." (PMID 20182538, 2009). "Bromodomain-containing protein 4 (BRD4) was recently found to play a critical role in endotoxemia colon by regulating NLRP3/caspase-1/GSDMD-mediated pyroptosis, and BRD4 inhibition could prevent endotoxemia-induced colon damage through blocking inflammation-related pyroptosis." (PMID 36505474, 2022). "Both the accumulation of inflammation cytokines especially IL18 and IL1β, and the activation of NLRP3/ASC/Caspase 1 inflammasome complex in damaged colon indicated that endotoxemia-induced colonic mucosa injury might be related with inflammation-related pyroptosis." (PMID 33679744, 2021). "qPCR analysis demonstrated that aging significantly increased expression of the inflammasome components pro-caspase-1, ASC, and NLRP3 in the liver during endotoxemia." (PMID 25847140, 2015). "In this study, JQ1 pretreatment inactivated the NLRP3/ASC/caspase 1 inflammasome assembly, and eliminated the elevation of gasdermins, which indicated BRD4 might promoted pyroptosis to lead endotoxemia colon injury." (PMID 33679744, 2021).
gastric cancer (18 papers, 2013 to 2025). A primary or metastatic malignant neoplasm involving the stomach. "For instance, high CASP1 mRNA expression has been associated with favorable outcomes in colorectal and stomach cancers, yet it correlates with adverse OS in acute myeloid leukemia." (PMID 38562170, 2024). "A similar observation was reported in gastric cells, in which loss of C1GALT1 activity is the cause of gastritis and gastric cancer by caspase-1/caspase-11 (Casp1/11)–dependent inflammasomes." (PMID 35207462, 2022). "Loss of caspase-1 in gene expression was associated with worse survival in patients with gastric cancer." (PMID 30042341, 2018). "Loss of caspase-1 gene expression has been observed in prostate and gastric cancers." (PMID 27705930, 2016). "Furthermore, the loss of Casp1 expression has been observed in 19.3% of gastric carcinomas." (PMID 24265764, 2013). "Our investigation commences with an integrative approach employing molecular docking and meticulous microscopic morphology assessments to postulate the impact of BA on Caspase-1, thereby instigating pyroptotic cell death in gastric cancer cells." (PMID 38169542, 2024). "To elucidate the underlying mechanism of how ALKBH4 inhibits pyroptosis in gastric cancer cells, we evaluated the impact of ALKBH4 expression on key targets (GSDME, GSDMD, NLRP3, Caspase 1) of the pyroptosis pathway using qPCR and western blot experiments." (PMID 38902235, 2024). "Increasing DDP-sensitivity in gastric cancer by inducing pyroptosis via regulating the caspase-1/GSDMD pathway." (PMID 38239395, 2023). "Pyroptosis is an inflammatory form of programmed cell death triggered by caspase-1/4/5/11 that plays an important role in the occurrence and development of gastric cancer (GC)." (PMID 35280928, 2021). "In gastric cancer, RBPMS2 is overexpressed, predicts poor prognosis, and promotes proliferation, invasion, and migration by suppressing NLRP3/caspase-1/GSDMD-mediated pyroptosis." (PMID 41562091, 2025). "miR-135a-5p targets CASP1, CXCL10, and transmembrane protein 140 (TMEM140), which are known to be involved in the proliferation of gastric cancer cells and the expression of IFN-α." (PMID 37952025, 2023). "Herein, we further showed that famotidine stimulation in gastric cancer cells of BGC823 and AGS significantly promoted cell pyroptosis by inducing NLRP3 activation, leading to caspase-1 activation, IL-1β and IL-18 release." (PMID 34686215, 2021). "Next, we treated these gastric cancer cells with the culture supernatants from M.hy challenged THP-1 derived macrophages or macrophages with silencing of NLRP3, ASC and caspase-1 for migration and invasion assay." (PMID 24223129, 2013). "Further results showed that famotidine triggered cell pyroptosis in gastric cancer cells by activation of NLPR3 inflammasomes including ASC, Caspase-1 and NLRP, leading to enhanced IL-18, not IL-1β, mature and secretion." (PMID 34686215, 2021).
Hepatitis (18 papers, 2015 to 2026). Inflammation of the liver. "Here, we reported that NLRP3 and caspase-1 were required for the activation of IL-1β in a murine model of ConA-induced AIH, and mice deficient in NLRP3 or caspase-1 (NLRP3−/− or caspase-1−/−) were protected from hepatitis." (PMID 29692782, 2018). "In brief, these results demonstrated that caspase-1 was required for IL-1β production in ConA-induced hepatitis and caspase-1 deficiency prevented NLRP3 inflammasome activation and pyroptosis, thus ameliorating liver inflammation and injury." (PMID 29692782, 2018). "Moreover, viral infected animals in deficiencies of NLRP3 and Caspase-1, two essential components of the inflammasome complex, also have reduced IL-1β induction along with ameliorated hepatitis." (PMID 26367131, 2015). "This phenotype is closely associated with abnormal activation of the NLRP3 inflammasome, a key driver of hepatitis that initiates inflammatory cascades through Caspase-1-mediated maturation of IL-1β and IL-18." (PMID 40868283, 2025). "Activated inflammasome initiates caspase-1 and determines IL-1β and IL-18 pro-inflammatory cytokines production, increasing liver inflammation, fibrosis, and damage in ADL and NAFLD." (PMID 38473721, 2024). "Over-expression of NLRP3 inflammasome and cleaved levels of caspase-1 were reported in Concanavalin A (ConA)-induced hepatitis animal model." (PMID 38026692, 2023). "Strikingly, NLRP3−/− and caspase-1−/− mice were broadly protected from hepatitis as determined by decreased histological liver injury, serum aminotransferase (ALT)/aspartate transaminase levels, and pyroptosis." (PMID 29692782, 2018). "In contrast to WT mice, caspase-1−/− mice developed ameliorated hepatitis, as exhibited by impaired histological liver injury and decreased serum ALT and AST levels, an outcome similar to that of NLRP3−/− mice." (PMID 29692782, 2018). "Therefore, the inhibitory effect of the MP on Casp1 activation holds great promise for alleviating liver inflammation." (PMID 41583017, 2026). "The results of Qiu T and others showed that taurine supplementation could reduce the protein expression of NLRP3, ASC and Caspase-1 in liver tissue in an arsenic trioxide (AS2O3)-induced mouse hepatitis model." (PMID 38560269, 2024). "Similarly, hepatitis C virus (HCV), another common pathogen causing hepatitis, induces NLRP3 activation through glycoproteins, resulting in ASC-SPECK formation and subsequent cell death via both caspase-1 and caspase-3 pathways." (PMID 38002346, 2023). "Upon sensing noxious signals, NLRP3 recruits pro-caspase-1 and the adaptor molecule ASC (apoptotic specklike protein-containing CARD), resulting in activation of caspase-1 as well as secretion of IL-1β and interleukin-18 (IL-18), which play a critical role in promoting liver inflammation." (PMID 29692782, 2018). "NLRP3 inflammasome activates caspase 1 and promotes the maturation and secretion of downstream pro-inflammatory cytokines such as IL-1β and IL-18, resulting in the occurrence of programed cell death (apoptosis, autophagy, pyroptosis), liver inflammation and fibrosis." (PMID 37122694, 2023). "In the livers of ConA‐induced hepatitis mice, the expression levels of NLRP3, CASP1, and IL1B are significantly upregulated." (PMID 41503678, 2026). "Furthermore, SIRT1 disruption or XBP1s overexpression in macrophages exacerbated APAP-triggered liver inflammation and augmented NLRP3/caspase-1 activity in MSC-administrated mice." (PMID 35842731, 2022). "Among these cytokines, TNF-α and IL-1β could be the critical mediators for development of ConA-induced hepatitis, since TNF-α-deficient mice and NLRP3- and caspase-1-deficient mice that do not produce IL-1β are almost protected from ConA-mediated liver damage." (PMID 33809904, 2021).
Hepatitis (continued). "Moreover, NLRP3−/− and caspase-1−/− mice displayed downregulated IL-1β expression and diminished hepatitis, indicating that NLRP3 and caspase-1 were essentially required for IL-1β secretion and also contributed to the development of ConA-induced hepatitis in mice." (PMID 29692782, 2018).
E. coli infection (17 papers, 2017 to 2025). "Here, we showed that global deficiency of caspase-1 can protect against lethal pulmonary Escherichia coli infection by reducing the necroptosis of infiltrated neutrophils, which are key players in immune responses in the lung." (PMID 40359428, 2025). "Since previous reports indicated that BA receptors FXR and TGR5 deficient macrophages had reduced caspase-1/11 activation and release of mIL-1β upon E. coli infection 28, there seem to be contradict in the regulation of BAs on the regulations of macrophages." (PMID 39664579, 2024). "Supporting these observations, Bmal1-deficient macrophages exhibited enhanced LDH release by E. coli infection, which also induced caspase-1/-11-dependent cell death." (PMID 38297162, 2024). "IFN-β priming and E. coli infection caused caspase-1/-11-dependent pyroptosis, indicating that these stimulants trigger caspase-11-mediated noncanonical inflammasome signaling." (PMID 38297162, 2024). "In mice, non-canonical caspase-11 was identified as a key regulator of NLRP3 inflammasome-associated caspase-1 activation in response to E. coli infection." (PMID 30087667, 2018). "Loss of CASP6 resulted in reduced CASP1 activation following E. coli infection." (PMID 34740613, 2021). "In LPS or E. coli infection, Txnip-deficient macrophages manifest the partial decrease of active caspase-1 and IL-1β production, which might result from increased S-nitrosylation of NLRP3 inflammasome components that hinder IL-1β maturation." (PMID 31620121, 2019). "Although we observed more tissue-resident macrophages in the Casp1-/- mice in the physiological state, these macrophages decreased dramatically at 12 hours post-E. coli infection." (PMID 40359428, 2025). "We showed that the activation of caspase-1 contributed to the pathophysiology of pulmonary E. coli infection and facilitated lung neutrophil necroptosis." (PMID 40359428, 2025). "In the present study, we found that the activation of caspase-1 exacerbated the pathophysiology of pulmonary E. coli infection by driving infiltrating neutrophil necroptosis." (PMID 40359428, 2025). "TMEM173 promoted calcium release from macrophages and monocytes ER, leading to activation of caspase-1/-11/-8 in a bacterial type-dependent manner (e.g., activated caspase-1/-11 in E. coli infection and activated caspase-8 in S. pneumoniae infection)." (PMID 38022612, 2023). "We also investigated the mRNA levels of the genes involved in the NLRP3/caspase-1/GSDMD pathway in cells after E. coli infection and found that ZB-1 infection significantly upregulated their expression levels." (PMID 37511208, 2023). "Next, we measured the mRNA levels of each gene in the NLRP3/caspase-1/GSDMD pathway after E. coli infection." (PMID 37511208, 2023). "Protein interaction network analysis revealed that the pyroptosis classic pathway NLRP3/caspase-1/GSDMD is involved in E. coli infection." (PMID 37511208, 2023). "Mechanistically, our results suggest the involvement of the NLRP3/caspase-1/GSDMD pathway in E. coli infection." (PMID 37511208, 2023). "Accompanying the decrease in ROS, NLRP3, Caspase-1 p10, and Caspase-3 p17 levels due to E. coli infection was mitigated by NAC, which indicated that E. coli-induced NLRP3 inflammasome and apoptosis activation required ROS production." (PMID 34594329, 2021). "Western blot and immunofluorescence analyses revealed that pre-incubation with L. rhamnosus GR-1 decreased E. coli-induced caspase-1 activation at 6 h after E. coli infection, as also observed in ASC-knockout MAC-T cells." (PMID 30087667, 2018). "Caspase-11 is activated via NLRP3-independent mechanisms, but it is essential for NLRP3-dependent and ASC-dependent caspase-1 processing and IL-1β maturation in response to E. coli infection." (PMID 30087667, 2018). "We next investigated cell death, which may account for the difference in the number of neutrophils in the lungs of Casp1-/- and Casp1+/+ mice after E. coli infection." (PMID 40359428, 2025).